EPCAM (epithelial cell adhesion molecule)
Diseases named in the same sentence as EPCAM in open-access papers (continued):
Sharing a sentence is not in itself a finding about the gene and the disease.
gastric cancer (95 papers, 2005 to 2025). A primary or metastatic malignant neoplasm involving the stomach. "Previous studies have also demonstrated a close association between EPCAM and the prognosis of gastric cancer." (PMID 37915566, 2023). "The results from clinical studies (NCT00836654) demonstrated that the application of catumaxomab is associated with the depletion of CD133+/EpCAM+ CSCs from malignant ascites in patients with the ovarian, pancreatic, and gastric cancer." (PMID 36900399, 2023). "For example, high EpCAM expression in primary renal cell carcinoma tumors was associated with improved patient survival, and in gastric cancer, loss of EpCAM expression was associated with aggressive tumor behavior." (PMID 37192201, 2023). "The pooled odds ratio (ORs) and 95% confidence intervals (CIs) were applied to estimate the associations between EpCAM and gastric cancer." (PMID 28403178, 2017). "Clinically, high expression of EpCAM was also notably associated with higher gastric carcinoma cell proliferation and disease progression." (PMID 28959019, 2017). "Similar immunological activity with increasing humoral and cellular immunity against different tumor-associated antigens was observed with the EpCAM-specific trifunctional antibody catumaxomab applied to gastric cancer patients in the adjuvant setting." (PMID 27387446, 2016). "Increased EpCAM expression is a poor prognostic marker in breast and gall bladder cancers, while it is associated with favorable prognosis in colorectal and gastric cancers." (PMID 25695234, 2015). "High EpCAM expression associates with proliferation and progression of gastric cancer, especially in the diffuse type." (PMID 23830302, 2013). "Expression of L1CAM and EPCAM in gastric cancer was significantly associated with lymph node and distant metastasis, and poor prognosis." (PMID 24422715, 2013). "The relative loss of EpCAM expression in patients with gastric cancer is associated with a significant reduction in survival, indicating that loss of EpCAM expression identifies aggressive tumours especially in patients with stage I and II disease." (PMID 17325709, 2007). "Moreover, EpCAM overexpression was associated with larger tumour size, lymphnode metastasis and worse prognosis in gastric cancer." (PMID 28403178, 2017). "Previously, we described an extended phenotype of gastric cancer stem cells (GCSCs; CD24+CD44+CD54+EpCAM+) that is associated with metastasis and tumor stage in GC patients." (PMID 39148939, 2024). "The role and mechanism of action of vinculin have been controversial, but this molecule may downregulate EpCAM (epithelial cellular adhesion molecule) and its own role in gastric cancer through DNA methylation, causing NK cells to enrich into tumor cells and kill tumor cells." (PMID 33535187, 2021). "The association of EpCAM expression with the progression of gastric cancer remains unclear." (PMID 23830302, 2013). "Furthermore, EpCAM has a direct effect on tumor cell proliferation by upregulation of c-myc and cyclin A/E and loss of E-cadherin expression is observed in undifferentiated-type gastric carcinomas upon mucosal spread and deep invasion beyond the submucosa." (PMID 16536871, 2006). "Detection of EpCAM+ CTCs using fluorescence-activated cell sorting (FACS) in gastric cancer showed high sensitivity (SV) and specificity (SP) of 92.3% and 100%, respectively." (PMID 40676582, 2025). "For instance, using the FACS technique, a cutoff of ≥ 3 CTCs EpCAM+ indicated gastric cancer with 100% specificity, demonstrating the importance of marker selection." (PMID 40676582, 2025). "Many CTCs have been reported that lack or express low level of EpCAM that can go undetected as reported in breast cancer and gastric cancer." (PMID 40676582, 2025). "A cohort study and flow cytometry analysis of 127 gastric cancer patients showed that CD24+CD44+CD54+ EpCAM+ cells were positively correlated with tumour metastasis and were present in untreated patients." (PMID 40665579, 2025).
gastric cancer (continued). "A cohort study of 127 untreated gastric cancer patients demonstrated that CD24+CD44+CD54+EpCAM+ cells are bona fide gastric CSCs." (PMID 40665579, 2025). "EVs derived from stomach cancer cells encapsulate proteins such asclaudin-7, CD44v6, CD44, c-MET, EGFR, EpCAM, and GPC1, all of whichare closely associated with the progression of gastric cancer." (PMID 40720603, 2025). "Early-phase human trials for patients with late-stage colorectal and gastric cancer have demonstrated the safety and efficacy of EpCAM CAR-T cell therapy (specifically, IMC001)." (PMID 39397869, 2024). "We have previously developed EpCAM-targeting CAR T cells for the treatment of gastric cancer, which demonstrated potent efficacy in achieving complete responses in subcutaneous gastric cancer models." (PMID 38550578, 2024). "Ultimately, under our conditions, we conclude that CD24+CD44+CD54+EpCAM+ cells are true gastric cancer stem cells (GCSCs)." (PMID 36737794, 2023). "We previously developed CAR T cells targeting epithelial cellular adhesion molecule (EpCAM) for the treatment of gastric cancer." (PMID 38067255, 2023). "Our data showed that BAP31 interacts with EpCAM in the ER and is positively correlated with N-glycosylated EpCAM in both gastric cancer cell lines and HEK-293 cells." (PMID 37834237, 2023). "The aim of this study was to elucidate the complex interactions between tumor cells and CAR T cells targeting epithelial cell adhesion molecule (EpCAM) in a xenograft model of gastric cancer." (PMID 38067255, 2023). "We have developed chimeric antigen receptor (CAR) T cells specifically targeting EpCAM for the treatment of gastric cancer." (PMID 38067255, 2023). "Next, we analyzed the expression of FOXO4, as well as the Wnt/β-catenin target and gastric cancer stem cell marker EpCAM in the human gastric cancer tissue arrays and the TCGA dataset." (PMID 35805009, 2022). "There are various markers for gastric cancer CTCs; for the epithelial subtype, they include EpCAm, cytokeratin (CK): CK8, CK18, and CK19 and for the mesenchymal subtype, they include vimentin and twist." (PMID 36428707, 2022). "As expected, a clinical trial also confirmed that EpCAM-targeted CAR-T cells are safe and effective in the treatment of EpCAM-positive gastric cancer." (PMID 35911706, 2022). "Despite this, most gastric cancers are EpCAM+, thus it must be used in conjunction with other more specific markers in identification of gastric CSCs." (PMID 33628765, 2021). "In order to clarify the role of EMT and distant metastasis, we first analyzed the mRNA expression of VIM, CDH1, S100A4 and EPCAM in human gastric cancer samples from the Cancer Genome Atlas (TCGA) data." (PMID 33535187, 2021). "To verify the effect of vinculin on tumor cells, we had knocked down vinculin in gastric cancer cell lines in vitro to verify the effect of vinculin on tumors, and found that vinculin can play an important role by regulating the expression of EPCAM." (PMID 33535187, 2021). "Catumaxomab has documented efficacy in a variety of EpCAM-overexpressing epithelial cancer subtypes like ovarian, breast, and gastric carcinoma." (PMID 32438548, 2020). "-Both CD44 and EpCAM markers are needed for isolation of cancer stem cells directly from patients. -In addition to in vivo experiments, gastric cancer stem cells generate various differentiated cells in cancer sphere culture." (PMID 31024835, 2019). "Consistently, immunoblot analysis revealed a significant difference between the protein expression levels of EpCAM and vimentin in both gastric cancer cell lines and fibroblasts." (PMID 31850215, 2019). "Fluorescence intensity analysis showed that all five gastric cancer cell lines were marked by global expression levels of EpCAM, while normal fibroblasts exhibited up-regulation of vimentin expression." (PMID 31850215, 2019).
gastric cancer (continued). "Using an immunofluorescence-based approach, we employed numerous gastric cancer cell lines and PDCs to assess tumor cell populations within each given tumor by analyzing the intensity of EpCAM and vimentin expression." (PMID 31850215, 2019). "Gastric cancer cell-lines and PDCs were subjected to multi-color immunofluorescence analysis against EpCAM and vimentin to evaluate the tumor cell index based on EpCAM expression levels." (PMID 31850215, 2019). "To identify tumor‐suppressive microRNAs repressed by DNA methylation in gastric cancer (GC), we analyzed the genome‐wide DNA methylation and microRNA expression profiles of EpCAM+/CD44+ GC cells." (PMID 29862663, 2018). "The binding affinity and selectivity of the Ep1 aptamer was analysed using an EpCAM-positive gastric cancer cell line, KATO III, and comparing it to an EpCAM-negative mouse fibroblast, NIH/3T3 cells." (PMID 30586898, 2018). "The SELEX technique was applied and the resulted sequences were tested on EpCAM-positive human gastric cancer cell line, KATO III, and the EpCAM-negative mouse embryonic fibroblast, NIH/3T3 cells." (PMID 29245156, 2017). "Regarding the biological properties of CSCs, numerous studies have indicated that the assessment of the EpCAM expression level in gastric cancer tissue sections is sensible." (PMID 28403178, 2017). "The I2 estimate revealed significant heterogeneity (I2 = 53%) among the studies, and the random effects model used in thismeta-analysis indicated that the expression of EpCAM in the gastric cancer group was greater than that in the control group." (PMID 28403178, 2017). "A total of eight studies reported EpCAM overexpression in gastric cancer groups (gastric cancer tissues) and control groups (pericarcinoma tissues or normal gastric tissues)." (PMID 28403178, 2017). "The meta-analysis demonstrated that the expression of EpCAM in the gastric cancer group was greater than that in the control group." (PMID 28403178, 2017). "The original results of meta-analyses revealed that the expression of EpCAM in the gastric cancer group was greater than that in the control group." (PMID 28403178, 2017). "A total of two studies reported the cumulative 5-year overall survival rates of the EpCAM-positive [EpCAM(+)] and EpCAM-negative [EpCAM(−)] gastric cancer patients." (PMID 28403178, 2017). "Despite some controversies, CD44, CD90 (Thy1), and EpCAM (CD326) are thought to enrich gastric cancer stem cells (GCSCs)." (PMID 27107424, 2016). "Catumaxomab, an anti-EpCAM monoclonal antibody, coupled with intraperitoneally administered paclitaxel are recommended to effectively relieve gastric cancer-derived peritoneal metastasis." (PMID 27270314, 2016). "A high level of EpCAM expression is prominent in gastric cancer, and a high level of IGSF4 expression is frequently observed in hepatocarcinomas." (PMID 27834817, 2016). "The intratumoral expression of EpCAM was assessed in 163 primary gastric cancers (61 diffuse-, 62 intestinal-, 32 mixed-type and 8 unclassified tumors) by immunohistochemistry, using the monoclonal antibody Ber-EP4." (PMID 23830302, 2013). "Expression of L1CAM and EPCAM were examined immunochemically in 601 clinicopathologically characterized gastric cancer cases." (PMID 24422715, 2013). "L1 cell adhesion molecule (L1CAM) and epithelial cell adhesion molecule (EPCAM) have been implicated in the development and progression of gastric cancer." (PMID 24422715, 2013). "The present study investigated the clinical significance of L1CAM and EPCAM in the development, progression and prognosis of gastric cancer." (PMID 24422715, 2013). "The authors revealed that EpCAM is overexpressed in gastric cancer and down-regulation of EpCAM resulted in a decrease of cell proliferation and suppressed tumor formation." (PMID 23830302, 2013). "Here, we investigated the expression of EpCAM in gastric cancer subtypes and correlated the data to tumor cell proliferation and clinicopathologic factors." (PMID 23830302, 2013).
gastric cancer (continued). "Statistical analysis revealed that diffuse type gastric cancers were characterised by significantly (p=0.036) higher EpCAM expression in the invasion front (28%) than in the tumor centre compared to the intestinal type;." (PMID 23830302, 2013). "In patients, strong expression of EpCAM mostly correlated with a diminished overall survival, whereas some entities such as gastric cancers displayed the opposite correlation, with increased survival in the presence of high-level EpCAM expression." (PMID 24009667, 2013). "Diffuse type gastric cancers exhibited a significantly weaker overall EpCAM expression than intestinal type cancers (p=0.008) or mixed type cancers." (PMID 23830302, 2013). "Using this system, we identified 77% of gastric carcinomas exhibiting de novo expression of EpCAM within the primary tumor, while normal gastric mucosa was devoid of EpCAM." (PMID 23830302, 2013). "The antibody VH-F12 significantly inhibited glycosylation of EpCAM which, subsequently, reduced the adhesion of gastric cancer cells, inducing cytotoxic autophagy, inhibiting the AKT-PI3K-mTOR signaling pathway, and, finally, resulting in proliferation inhibition both in vitro and in vivo." (PMID 37834237, 2023). "Furthermore, we analyzed the relationship of BAP31 with 84 kinds of tumor-associated antigens and found that overexpression of BAP31 in gastric cancer cell line MKN-45 increased the protein levels of EpCAM." (PMID 37834237, 2023). "Therefore, the results suggested that suppressing the N-glycosylation of EpCAM by VH-F12 induces autophagic cell death via PI3K/Akt/mTOR pathway in gastric cancer cells." (PMID 37834237, 2023). "Notably, when we co-cultured NCI-N87 gastric cancer cells with normal fibroblasts at various cell-to-cell concentrations, we observed a significant correlation between EpCAM and vimentin fluorescent intensity levels." (PMID 31850215, 2019). "Finally, we investigated the relation of the expression of EpCAM with clinicopathological factors and its impact on prognosis in gastric cancer." (PMID 23830302, 2013). "Moreover, we noticed in our study differential EpCAM expression patterns in the diverse types of gastric cancers according to the classification by Lauren." (PMID 23830302, 2013). "This study investigated the expression pattern of EpCAM and its prognostic value in gastric cancer." (PMID 23830302, 2013). "Considering the discontenting results of the current adjuvant concepts for gastric cancer patients, EpCAM might be target in the adjuvant therapy of this malignant disease." (PMID 23830302, 2013). "In EpCAM-positive tumors catumaxomab, an antibody that specifically binds EpCAM-positive tumor cells and CD3+ T-lymphocytes, showed an acceptable safety profile and promising treatment efficiency, suggesting EpCAM to be an important target in the therapy of gastric cancer." (PMID 23830302, 2013). "EPCAM was found to be overexpressed in gastric cancer tissues." (PMID 24422715, 2013). "Furthermore, our study disclosed a significant correlation between high EpCAM expression and high tumor cell proliferation, suggesting that EpCAM promotes proliferation and progression of gastric cancer in vivo." (PMID 23830302, 2013). "Considering the discontenting results of the current (neo-) adjuvant concepts for gastric cancer patients, additional therapeutic EpCAM-targeting might be a beneficial concept for multimodality therapy of this malignant disease." (PMID 23830302, 2013). "Our study showed high expression of EPCAM protein was detected in 247(41.1%) gastric cancers." (PMID 24422715, 2013). "The study revealed that depth of invasion (P=0.007), lymph node (P = 0.009) and distant metastasis (P = 0.01), TNM stage (P = 0.008), expression of L1CAM (P = 0.007), and of EPCAM (P = 0.009) were independent prognostic factors in patients with gastric carcinoma." (PMID 24422715, 2013). "Therefore, CD44+EpCAM+ cells were selected as gastric cancer stem cells for subsequent experiments." (PMID 36765401, 2023).
gastric cancer (continued). "Indeed, with sufficient understanding of the biological properties of EpCAM and improvements in the technology of the production EpCAM monoclonalantibodies, EpCAM-targeted immunotherapy will likely be an exciting and promising strategy for the treatment of metastatic gastric cancer." (PMID 28403178, 2017). "In conclusion, high EpCAM expression is possibly closely related to the clinicopathological parameters of GC patients, and EpCAM might play a critical role in the pathophysiology of gastric cancer." (PMID 28403178, 2017). "De novo expression of EpCAM could be observed in 77% (n=126) of gastric cancers." (PMID 23830302, 2013). "The count of EpCAM- carcinoembryonic antigen (CEA)+ cells was significantly higher in gastric cancer patients with stage II-III and IV compared to those with stage I. Patients with high EpCAM-CEA+ cell counts had a reduced 3-year RFS." (PMID 40676582, 2025). "CD44v6 was markedly upregulated in gastric cancer tissues, correlating with a worse prognosis and enhancing CSC traits by increasing the expression of key markers such as CD44, CD133, and EpCAM, as well as key transcription factors like Oct-4 and Nanog." (PMID 40069421, 2025). "Studies have indicated that antigens like HER2, CEA, MUC1, Claudin 18.2 (CLDN 18.2), EpCAM, B7H3, MSLN, and NKG2D serve as effective targets for CAR-T cell therapy in gastric cancer." (PMID 38622705, 2024). "We previously analyzed the relationship of BAP31 with 84 kinds of tumor-associated antigens and found that when BAP31 was overexpressed in the gastric cancer cell line MKN-45, protein levels of EpCAM were increased significantly." (PMID 37834237, 2023). "The ability of CAR T cells to influence gastric cancer has been extensively investigated, and includes research on epithelial growth factor receptor (EGFR), epithelial cell adhesion molecule (EpCAM), and mesothelin, and has also focused on NKG2D." (PMID 36618357, 2022). "In the previous related analysis, we found that there are a group of potential cancer stem cells in the single cells derived from gastric cancer tissues, which specifically express ALDH1A2 and EPCAM." (PMID 35659682, 2022). "It contains a potential gastric cancer cell (ALDH1A2 + and EPCAM +) completely derived from gastric cancer tissue, and ALDH1A2 is a marker of ovarian cancer cancer stem cell." (PMID 35659682, 2022). "EpCAM expression was positively correlated with the expression of CTNNB1 in LUAD, COAD, ESCA, LUSC, and stomach cancer." (PMID 34790117, 2021). "By analyzing the DNA methylation data of TCGA gastric cancer database, there were 12 DNA methylation sites in VIM, 8 in CDH1, 3 in S100A4, 7 in EPCAM, and 6 in VCL." (PMID 33535187, 2021). "Catumaxomab (Removab) and MT110, both targeting epithelial cell adhesion molecule (EpCAM) and CD3, were investigated in various cancers such as ovarian and gastric cancer in phase II or III clinical trials." (PMID 33086754, 2020). "EpCAM (EpC) is a putative CSC marker in liver, pancreatic, breast, and gastric cancer and interacts with cld7 to interfere with cell–cell adhesion, thus enhancing tumor cell migration." (PMID 30467381, 2019). "The epithelial cell adhesion molecule (EpCAM) is one of the most commonly used markers of cancer stem cells (CSCs), but the clinical and prognostic significance of EpCAM in gastric cancer (GC) remains disputable." (PMID 28403178, 2017). "We found a decreased expression of the epithelial markers CDH1, EpCAM, and increased expression of the mesenchymal markers CDH2, Vimentin, ZEB1, Snail, MMP14 and Twist in un-captured cells in gastric cancer cell lines AGS, SGC7901 and BGC-823." (PMID 27654478, 2016). "Evidence now supports that Bispecific T cell engagers (BiTEs) are highly effective in targeting CEA with MT111 for colorectal, ovary, and stomach cancer, CD19 for acute lymphatic leukemia (Blinatumomab) and EpCAM for cancer related ascites (Catumaxomab)." (PMID 27650544, 2016).